PGR (progesterone receptor)
Diseases named in the same sentence as PGR in open-access papers (continued):
Sharing a sentence is not in itself a finding about the gene and the disease.
breast cancer (continued). "In addition to its role in ER+ BCs, KDM5B contributes to BC progression in triple-negative breast cancer (TNBC), a highly aggressive subtype of breast cancer defined by a lack of ER, progesterone receptor, and human epidermal growth factor receptor 2 (HER2) expression." (PMID 36509829, 2022). "Furthermore, the associations between protein levels and survival of patients was the most obvious in the KM curves revealing the expression of CAVIN2 and RFS of HER2 negative, progesterone receptor (PR) positive, and estrogen receptor (ER) positive breast cancer." (PMID 34513683, 2021). "Breast cancer is a heterogeneous group of diseases, which is broadly classified in the clinic into three major subtypes based on the expression or absence of estrogen receptor (ERα), progesterone receptor (PR), and human epidermal growth factor receptor-2 (HER2)." (PMID 34532657, 2021). "In addition, three case-only studies found that the relative proportion of ER− breast cancer and/or triple negative (ER−, progesterone receptor negative, HER2 negative) breast cancer was higher among women residing in lower SES neighborhoods than among women residing in higher SES neighborhoods." (PMID 34809694, 2021). "Moreover, other studies have shown that Ob-R might be an independent biomarker for different types of breast cancer, not correlating with ER/PgR or HER2 status." (PMID 34210055, 2021). "Based on the status of estrogen receptor (ER), progesterone receptor (PR) and human epidermal growth factor receptor (HER2), different intrinsic subtypes of BC have been classified as: luminal A, luminal B, HER2-enriched and triple negative breast cancer (TNBC)." (PMID 33691613, 2021). "However, triple negative breast cancers—the collective term for breast cancers that do not express the estrogen receptor (ER) and the progesterone receptor (PR), and do not overexpress the human epidermal growth factor receptor type 2 (HER 2)—are resistant to most types of targeted therapies." (PMID 33924764, 2021). "Triple negative breast cancer (TNBC) represents about 14–16% of all BC patients and is characterized by lack of estrogen receptor (ER), progesterone receptor (PR), and HER2 expression." (PMID 34900718, 2021). "Based on the expression of estrogen receptor (ER), progesterone receptor (PR), human epidermal growth factor 2 (HER2), and proliferation marker protein Ki-67, BC can be categorized into four subtypes including luminal A, luminal B, HER2, and triple-negative breast cancer (TNBC)." (PMID 33824695, 2021). "Therefore, for the present study, we established a cohort of 116 patients afflicted with triple-negative breast cancer (TNBC), which accounts for approximately 10–15% of all breast cancers and is defined by the absence of estrogen receptor (ER), progesterone receptor (PR), and HER2 overexpression." (PMID 32028882, 2020). "In clinical practice, the expression of the estrogen receptor (ER), progesterone receptor (PR), and the human epidermal growth factor receptor 2 (HER2) identifies three main subgroups: Luminal or hormone receptor positive (HR-positive) BC, HER2-positive BC, and triple negative breast cancer (TNBC)." (PMID 31450641, 2019). "Triple Negative Breast Cancer (TNBC) subtypes represent 10% to 20% of BC and are characterized by the lack of progesterone receptor, estrogen receptor and human epidermal growth factor receptor 2 expression." (PMID 31340603, 2019). "According to one report, among 14,599 breast cancer patients with BM, the ER positive rate was 37% (41% negative and the others unknown), the PgR positive rate was 36% (34% negative), the HER-2 positive rate was 35% (41% negative), and the triple negative rate was 27% (18% triple positive)." (PMID 31603918, 2019).
breast cancer (continued). "In conclusion, high expression of angiogenesis-related proteins is associated with adverse clinicopathological parameters in early-stage breast cancer patients and may be surrogate markers of biologically distinct subgroups of ER/PgR-negative or TNBC tumors with superior outcome." (PMID 30063723, 2018). "In conclusion, high expression of angiogenesis-related proteins is associated with adverse clinicopathological parameters in early-stage breast cancer patients and may be surrogate markers of biologically distinct subgroups of ER/PgR-negative or triple-negative tumors with superior outcome." (PMID 30063723, 2018). "By detecting the expression levels of ER and progesterone receptor (PgR), as well as the HER2 and Ki-67, BC were identified into categories with similar clinical implications, including Luminal A, Luminal B, HER2-positive, and triple-negative breast cancer (TNBC) subtypes." (PMID 30400599, 2018). "Thus, many of the 430 breast-cancer related genes may not be predictive of histologic grades but are expected to be highly correlated with the mandatory covariates, i.e. ER and PgR statuses." (PMID 28122498, 2017). "The ER/PgR status is no longer sufficient to treat breast cancer patients in Ivory Coast since the human epidermal growth factor receptor 2 (Her2) overexpression analysis and the Ki67 index are required to define the molecular classification of breast cancers for better treatment strategies." (PMID 28173783, 2017). "In contrast, triple-negative breast cancer (TNBC), BC without ER/PgR expression or HER2 overexpression, has heterogeneous histologic characteristics, no identified therapeutic target molecules, and a dismal prognosis." (PMID 28060723, 2017). "Moreover, metastases from breast carcinoma may exhibit negative ER and PgR staining, even if the primary breast cancer is positive for ER and PgR." (PMID 27957354, 2016). "Therefore, immunostaining for ER and PgR may not be able to definitively differentiate between breast cancer metastases and primary gastric cancers." (PMID 27957354, 2016). "Immunochemically, the ERα (estrogen receptor α)-positive breast cancer, the most common breast cancer subtype, can be distinguished from Her2 (human epidermal receptor 2)-positive and triple negative breast cancers (negative for ERα, Her2 and progesterone receptor)." (PMID 26515727, 2015). "However, the regulatory characteristics of miRNAs in triple-negative breast cancer, a phenotype of breast cancer that does not express the genes for estrogen receptor, progesterone receptor, and human epidermal growth factor receptor 2, are still poorly understood." (PMID 25888956, 2015). "While expression levels for SNED1 and LTBP3 were not significantly correlated across all mammary cancer sub-types, they were significantly correlated (p values of 0.0079 and 0.034, respectively) with poor prognosis for estrogen-receptor-negative and progesterone-receptor-negative (ER−/PR−) patients." (PMID 24618895, 2014). "Finally we demonstrated a strong positive correlation between Rictor and PgR expression and a negative correlation with Raptor expression in Luminal B breast cancer samples, a breast cancer histological subtype known for having an altered ERα-signaling pathway." (PMID 25283550, 2014). "We demonstrate that IC30 is a robust prognostic biomarker to predict clinical outcome in breast cancer, and is independent of standard clinical and pathological prognostic factors including patient age, lymph node status, tumor size, tumor grade, ER status, and progesterone receptor (PR) status." (PMID 24053408, 2013). "However, a significant subset of breast cancers cannot be treated by these therapies because they do not express ERα or its surrogate predictive marker of response, the progesterone receptor (PR), and/or these cancers commonly show resistance to drugs that target the ERα pathway." (PMID 22321971, 2012).
breast cancer (continued). "Nevertheless, dose-dense chemotherapy for early-stage breast cancer remains an important strategy as it is predicted to maximise the impact of individual cytotoxic agents, with encouraging results on long-term outcome, especially in ER-negative and PgR-negative tumours." (PMID 22009030, 2011). "However, the incidence of the biologically aggressive estrogen receptor (ER) negative, progesterone receptor (PR) negative breast cancer in women younger than 40 has been increasing in African Americans in the U.S., Nigerian, Chinese, Vietnamese, and Taiwanese populations." (PMID 20459777, 2010). "Breast cancer is commonly classified into four major clinical subtypes according to the presence or absence of molecular markers for estrogen receptor (ESR), progesterone receptor (PGR), and human epidermal growth factor receptor 2 (HER2)." (PMID 41510152, 2026). "Triple-negative breast cancer (TNBC) is a subtype defined by lacking estrogen receptor, progesterone receptor expression, and human epidermal growth factor receptor 2 (HER2) overexpression/amplification, which constitutes 10% to 20% of all breast cancers." (PMID 40735463, 2025). "A major subtype, triple-negative breast cancer (TNBC), is characterized by the lack of expression of estrogen receptor (ER), progesterone receptor (PR), and HER2 (ERBB2), and accounts for approximately 15 % of all breast cancer cases." (PMID 40822245, 2025). "TNBC, clinically defined by the absence of estrogen receptor (ER), progesterone receptor (PR) and human epidermal growth factor receptor 2 (HER2) expression, forms about 20% of all breast cancer cases." (PMID 39942711, 2025). "Out of the presence or absence of three of them, ESR1 (oestrogen receptor), PGR (progesterone receptor), and HER2/ERBB2 (human epidermal growth factor receptor 2/HER2) make a breast cancer triple positive or triple negative." (PMID 40690373, 2025). "Triple negative breast cancer (TNBC) is characterized by the absence of estrogen receptor (ER), progesterone receptor (PgR) and human epidermal growth factor receptor 2 (HER2), accounting for 15–20% of all breast cancers." (PMID 40783751, 2025). "Among breast cancer subtypes, TNBC is an aggressive subtype characterized by the absence of estrogen receptor (ER), progesterone receptor (PR), and human epidermal growth factor receptor 2 (HER2), resulting in limited therapeutic options and poorer outcomes." (PMID 40046748, 2025). "TNBC is specifically defined by the absence of estrogen receptor (ER), progesterone receptor (PR), and HER-2, accounting for approximately 15% of all breast cancer cases." (PMID 40949144, 2025). "Triple-negative breast cancer (TNBC) is a breast cancer subtype without human epidermal growth factor receptor 2 (HER-2), estrogen receptor (ER), and progesterone receptor (PR) expression." (PMID 40076939, 2025). "Eligible patients had oestrogen/progesterone receptor positive and HER2 negative breast cancer with 1–3 involved lymph nodes." (PMID 40214845, 2025). "Most of these ER-positive/HER2-negative breast cancers have a more indolent course than breast cancers that are HER2-positive or triple-negative (not expressing ER, the progesterone receptor (PR), or HER2)." (PMID 40647549, 2025). "Among breast cancer subtypes, TNBC is a highly aggressive form characterized by the lack of estrogen receptor (ER), progesterone receptor (PR), and human epidermal growth factor receptor 2 (HER2), accounting for approximately 15-20% of all breast cancer cases." (PMID 40438115, 2025). "A subset of advanced breast cancers are diagnosed as triple-negative breast cancer (TNBC), lacking expression of the estrogen receptor (ER), progesterone receptor (PR), and the Her2 tyrosine kinase receptor." (PMID 40754248, 2025).
breast cancer (continued). "Comprising 15–20% of all breast cancer cases, triple‐negative breast cancer (TNBC) is an aggressive subtype characterized by the lack of expression of estrogen receptor (ER), progesterone receptor (PR), and human epidermal growth factor receptor type 2 (HER2)." (PMID 40652528, 2025). "Triple‐negative breast cancer (TNBC), defined by lacking oestrogen receptor (ER), progesterone receptor (PR), and HER2 (Human Epidermal Growth Factor Receptor 2) expression, represents the most aggressive subtype of breast cancer." (PMID 41020311, 2025). "Basal‐like breast cancer (BLBC), overlapping with the subgroup of estrogen receptor (ER), progesterone receptor (PR), and HER2 triple‐negative breast cancer, has the worst prognosis and limited therapeutics." (PMID 39888288, 2025). "Cores from breast cancer tumors from the NHB cohort most frequently scored negative for estrogen receptor (63%, P < 0.005) and progesterone receptor (80%, P < 0.005) and most frequently have high expression of the Ki-67 proliferation marker (38%, P < 0.05)." (PMID 40309949, 2025). "Her previously documented immunohistochemistry revealed estrogen receptor (ER)-negative, progesterone receptor (PR)-negative, and human epidermal growth factor 2 (HER2) receptor-positive breast cancer." (PMID 38836153, 2024). "Unlike other subtypes of breast cancer, TNBC lacks the expression of estrogen receptor (ER), progesterone receptor (PR) and human epidermal growth factor receptor 2 (HER2), making it particularly challenging to treat." (PMID 38791158, 2024). "Triple-negative breast cancer (TNBC) is a particularly aggressive subtype of BC that is characterized by the absence of estrogen/progesterone receptor, and HER2 expression, constituting 15–20% of all breast cancers." (PMID 38956424, 2024). "TNBC is characterized by the absence of estrogen receptor, progesterone receptor, and HER2 expression (hence the name “triple negative”) and accounts for 15%–20% of breast cancer cases." (PMID 39456574, 2024). "Triple-negative breast cancer (TNBC), characterized by the absence of estrogen receptor (ER), progesterone receptor (PR), and human epidermal growth factor receptor 2 (HER2), accounts for 10–15% of all breast cancers." (PMID 38256428, 2024). "This case study presents a significant clinical response to anlotinib treatment in a patient with estrogen receptor-negative, progesterone receptor-positive, and human epidermal growth factor receptor 2 (HER2)-positive breast cancer, complicated by BM." (PMID 39224773, 2024). "SCD1 is highly expressed in breast cancer patients, particularly those with triple-negative and HER2-positive cells, where estrogen receptor and progesterone receptor expression are negative." (PMID 39468100, 2024). "In breast cancer, low TCL6 expression independently predicts an adverse outcome for PR (estrogen and progesterone receptor)-negative patients, while also correlating with immune infiltrating cells, including B cells, CD4+ T cells, and CD8+ T cells." (PMID 38605944, 2024). "Triple-negative breast cancer (TNBC) is an aggressive breast cancer subtype that does not express the estrogen receptor (ER), epidermal growth factor receptor 2 (HER2) or progesterone receptor (PR)." (PMID 38473871, 2024). "Triple-negative breast cancer (TNBC) is a highly malignant carcinoma with negative expression of estrogen receptor (ER), progesterone receptor (PR), and human epidermal growth factor receptor 2 (HER2), accounting for 15–25% of all breast cancers." (PMID 39054545, 2024). "Triple-negative breast cancer (TNBC) is characterized by the absence of estrogen receptor (ER), progesterone receptor (PR) and human epidermal growth factor receptor-2 (HER-2), accounting for 12 − 17% of all breast cancer cases." (PMID 38555429, 2024).
breast cancer (continued). "BC is further categorised depending upon the expressing hormone receptor such as the estrogen receptor (ER+), the human epidermal growth receptor 2 (HER2+), the progesterone receptor (PR+) and triple-negative breast cancer (TNBC), i.e., ER, PR, and HER2-all negative." (PMID 37443570, 2023). "Triple-negative breast cancer (TNBC) is characterized by the lack of estrogen receptor (ER), progesterone receptor (PR), and human epidermal growth factor receptor 2 (HER2), accounting for approximately 15%–20% of all breast cancers." (PMID 37274773, 2023). "ER-, PgR-negative, HER2-0, or HER2-low-expressing triple-negative breast cancer (TNBC) account for 15-20% of all breast cancers." (PMID 37051545, 2023). "Xpert Breast Cancer STRAT4 is a RT-qPCR platform that studies the mRNA expression of ESR1, PGR, MKI67 and ERBB2, providing a positive or negative result for each of these breast cancer biomarkers." (PMID 36980575, 2023). "The TNBC subtype is chracterized by lacking expression of the estrogen receptor (ER), progesterone receptor (PR), and human epidermal growth factor receptor 2 (HER2), representing 5-10% of all breast cancers." (PMID 36424525, 2023). "The presence or absence of estrogen receptor (ER), progesterone receptor (PR), and human epidermal growth factor receptor 2 (HER2) molecularly determines breast cancer subtypes." (PMID 38169859, 2023). "Approximately 10–20% of breast cancers are triple‐negative breast cancer (TNBC), a subtype characterized by immunohistochemical lack of estrogen receptor (ER), progesterone receptor (PgR), and human epidermal growth factor receptor 2 (HER2) overexpression." (PMID 37143440, 2023). "All ERBB2-amplified breast cancers were HER2-positive (over-expression) clinically, with most being ER- and progesterone receptor (PR)-negative and were diagnosed evenly with early- (Group 1 and Group 2A, n = 9) and late-stage disease (n = 7)." (PMID 37760445, 2023). "Clinically, TNBC is defined as the subtype tested negative for estrogen receptor (ER), progesterone receptor (PR) and human epidermal growth factor receptor 2 (HER2), accounting for 15–20% of all breast cancers." (PMID 37667382, 2023). "It is characterized by the absence of estrogen receptor (ER), progesterone receptor (PR), and human epidermal growth factor receptor 2 (HER-2 receptor 2, HER-2) expression and accounts for 10–20% of all breast cancers." (PMID 37391802, 2023). "Among all breast cancers, the subtype triple-negative breast cancer (TNBC) makes up 15 to 20%, which is defined as estrogen receptor (ER)-negative, progesterone receptor (PR)-negative, and human epidermal growth factor receptor-2 (HER-2)-negative." (PMID 36983708, 2023). "Triple-negative breast cancer (TNBC), also known as estrogen receptor-negative (ER-), progesterone receptor-negative (PR-), and human epidermal growth factor receptor 2-negative (HER2-) breast cancer, accounts for 15~20% of newly diagnosed breast cancers." (PMID 38123542, 2023). "Triple-negative breast cancer (TNBC) is a subtype of breast cancer, which is defined as the lack of progesterone receptor, estrogen receptor (ER), and human epidermal growth factor receptor 2 (HER2), and about 10–20% of breast cancer is TNBC." (PMID 37658975, 2023). "Breast cancer cell lines MDA-MB-231 and HS578T are basal and so-called triple negative, which means neither estrogen receptor (ER) and progesterone receptor (PR) nor human epidermal growth factor receptor 2 (HER2) are expressed." (PMID 37445874, 2023). "The surgically removed metastatic lung nodule was diagnosed as an estrogen receptor (ER)-positive, progesterone receptor (PgR)-negative, and human epidermal growth factor receptor 2 (HER2)-negative metastatic adenocarcinoma of breast cancer origin." (PMID 37692183, 2023).